CLASP2 (cytoplasmic linker associated protein 2)
Description:
Microtubule plus-end tracking protein that promotes the stabilization of dynamic microtubules. Involved in the nucleation of noncentrosomal microtubules originating from the trans-Golgi network (TGN). Required for the polarization of the cytoplasmic microtubule arrays in migrating cells towards the leading edge of the cell. May act at the cell cortex to enhance the frequency of rescue of depolymerizing microtubules by attaching their plus-ends to cortical platforms composed of ERC1 and PHLDB2. This cortical microtubule stabilizing activity is regulated at least in part by phosphatidylinositol 3-kinase signaling. Also performs a similar stabilizing function at the kinetochore which is essential for the bipolar alignment of chromosomes on the mitotic spindle. Acts as a mediator of ERBB2-dependent stabilization of microtubules at the cell cortex.
Synonyms: KIAA0627
Tractability: Small molecule: a structure with a bound ligand is known. Antibody: UniProt places it where antibodies can reach, with high confidence; its Gene Ontology location is reachable by antibodies, with high confidence. PROTAC: ubiquitination databases record sites on it; its protein half-life has been measured.
Gene: Protein-coding gene on chromosome 3 (33,496,187 to 33,718,414, reverse strand). Ensembl gene ENSG00000163539.
Subcellular location: Cytoplasm, cytoskeleton; Cytoplasm, cytoskeleton, microtubule organizing center, centrosome; Chromosome, centromere, kinetochore; Cytoplasm, cytoskeleton, spindle; Golgi apparatus; Golgi apparatus, trans-Golgi network; Cell membrane; Cell projection, ruffle membrane; Cytoplasm, cell cortex
Subcellular location (Human Protein Atlas): Golgi apparatus; Cytosol
Pathways (Reactome):
Cell Cycle: Amplification of signal from unattached kinetochores via a MAD2 inhibitory signal; EML4 and NUDC in mitotic spindle formation; Mitotic Prometaphase; Resolution of Sister Chromatid Cohesion; Separation of Sister Chromatids
Developmental Biology: Role of ABL in ROBO-SLIT signaling
Signal Transduction: RHO GTPases Activate Formins
Gene Ontology:
Molecular function: dystroglycan binding; microtubule binding; microtubule plus-end binding; protein binding
Biological process: basement membrane organization; exit from mitosis; Golgi organization; microtubule anchoring; microtubule cytoskeleton organization; microtubule nucleation; microtubule organizing center organization; mitotic spindle organization; negative regulation of focal adhesion assembly; negative regulation of stress fiber assembly; negative regulation of wound healing, spreading of epidermal cells; positive regulation of epithelial cell migration; positive regulation of exocytosis; positive regulation of extracellular matrix disassembly; presynaptic cytoskeleton organization; regulation of microtubule polymerization or depolymerization; regulation of microtubule-based process; vesicle-mediated transport; establishment of mitotic spindle localization; establishment or maintenance of cell polarity; mitotic spindle assembly; negative regulation of microtubule depolymerization; regulation of focal adhesion assembly
Cellular component: basal cortex; cell cortex; cell leading edge; cytoplasmic microtubule; focal adhesion; glutamatergic synapse; Golgi apparatus; kinetochore; membrane; microtubule; mitotic spindle; plasma membrane; ruffle membrane; trans-Golgi network; cytoplasm; cytosol; kinetochore microtubule; microtubule associated complex; microtubule organizing center; spindle microtubule; centrosome; cortical microtubule cytoskeleton; cytoskeleton; spindle
Genetic constraint (gnomAD): Loss-of-function variants: 25 observed, 95.78 expected, observed/expected ratio (o/e) 0.26, 90% interval 0.19 to 0.37. The upper end of that interval is the gene's LOEUF score, 0.37, which puts it in group 1 of 6, group 1 being the genes least tolerant of losing a copy. Missense variants: 983 observed, 1,226.6 expected, observed/expected ratio (o/e) 0.8, 90% interval 0.76 to 0.85. Synonymous variants: 464 observed, 451.92 expected, observed/expected ratio (o/e) 1.03, 90% interval 0.95 to 1.11.
Homologues: Orthologues: chimpanzee CLASP2 (99% identical), macaque CLASP2 (99% identical), pig CLASP2 (97% identical), rat Clasp2 (96% identical), guinea pig CLASP2 (94% identical), rabbit CLASP2 (88% identical), mouse Clasp2 (82% identical), zebrafish clasp2 (75% identical), Drosophila melanogaster chb (31% identical), Caenorhabditis elegans cls-1 (22% identical), Caenorhabditis elegans cls-2 (18% identical), Caenorhabditis elegans cls-3 (17% identical). Paralogues in human: CLASP1 (70% identical), TOGARAM1 (16% identical), TOGARAM2 (11% identical).
Diseases named in the same sentence as CLASP2 in open-access papers:
CLASP2 is named in the same sentence as 21 diseases in open-access papers, as found by Europe PMC text mining. Sharing a sentence is not in itself a finding about the gene and the disease. The quoted sentences say what the papers report.
bladder cancer (4 papers, 2017 to 2025). "Specifically, tumor necrosis factor-alpha (TNF-α) drives bladder cancer metastasis via METTL3-mediated m6A modification of cytoplasmic Linker associated protein 2 (CLASP2)." (PMID 40986143, 2025). "The introduction of exogenous CLASP2 in bladder cancer cell lines exerted in vitro cell migration and invasion." (PMID 36188577, 2022). "CLASP2 has been linked to the EMT and early progression of bladder cancer and has also been shown to predict bladder cancer prognosis." (PMID 34872548, 2021). "In our study, ectopic introduction of CLASP2 resulted in increased growth and aggressive phenotype of bladder cancer cells." (PMID 28166762, 2017). "In present study, we confirmed that manipulation of expression of CLASP2 could change the status of EMT in bladder cancer cell lines in vitro." (PMID 28166762, 2017). "We thought the reason of different roles of CLASP2 reported in two studies might be due to the different cell models (chicken epiblast cells vs. bladder cancer cells)." (PMID 28166762, 2017). "Additionally, the information on CLASP2 was limited only to bladder cancer, and investigations in other malignancies could provide benefits for clinical applications." (PMID 36188577, 2022). "First, we confirmed the relationship between CLASP2 and EMT in bladder cancers, but the results were descriptive." (PMID 28166762, 2017). "Four bladder cancer cell lines including J82, HTB 9, CRL1749 and T24 were tested the expression of CLASP2 at protein level." (PMID 28166762, 2017). "No significance of CLASP2 in bladder cancer or urine has been reported." (PMID 28166762, 2017).
Infertility (2 papers, 2022 to 2023). "Interestingly, one recent study observed that ablation of the CLIP-170 protein (belonging to the same family of proteins as CLASP2) is associated with abnormal nucleus shapes of spermatozoa and consequent infertility." (PMID 38066968, 2023).
Azoospermia (1 paper, 2022). Absence of any measurable level of sperm,whereby spermatozoa cannot be observed even after centrifugation of the semen pellet. "In total, we found nine genes that were recorded to be associated with “male infertility” or “non-obstructive azoospermia,” and three of them (CLASP2, CRACR2A, SOX5) were identified in this study as zebrafish testis cell-type specific marker genes." (PMID 35360857, 2022).
bladder tumor (1 paper, 2017). "RT-PCR was used to test the mRNA levels of CLASP2 and EMT-related markers (E-cadherin and Vimentin) in bladder tumor and urines." (PMID 28166762, 2017).
bladder urothelial cancer (1 paper, 2017). "CLASP2 is involved in the EMT and progression of bladder urothelial cancer." (PMID 28166762, 2017). "In conclusion, CLASP2 is involved in the EMT and progression of bladder urothelial cancer." (PMID 28166762, 2017). "Thus we speculated that CLASP2 might be involved in the EMT and progression of bladder urothelial cancer." (PMID 28166762, 2017).
co-infection (1 paper, 2023). "We hypothesized that the oncogenesis and process of HIV/HBV co-infection in HCC patients are exceedingly complex, and CLASP2 is one of the numerous pathogenic elements of HCC." (PMID 38022651, 2023).
colorectal cancer (1 paper, 2023). A primary or metastatic malignant neoplasm that affects the colon or rectum. "In the HMF colorectal cancers, we discovered eight predictive gene deficiency models (MSH3, SMC2, SMC6, BMPR2, CLASP2, SRCAP, UBR5, and UVRAG) of monoallelic LOF with PR-AUC-E ranging from 0.21 (CLASP2) to 0.62 (MSH3) (AUROC ranging from 0.68 for SRCAP deficiency to 0.94 for MSH3 deficiency)." (PMID 36883553, 2023).
lung carcinoma (1 paper, 2022). "Increasing microtubule instability may cause genetic instability, and altered expression of CLASP2 may induce genetic instability and contribute to the development of lung cancer." (PMID 35658861, 2022).
melanoma (1 paper, 2025). A malignant, usually aggressive tumor composed of atypical, neoplastic melanocytes. "For example, the paralog pair CLASP1/CLASP2 displayed a much stronger genetic interaction effect in lung and pancreatic models than in melanoma models (P = 0.0001, FDR: 0.011)." (PMID 40968372, 2025).
neuroblastoma (1 paper, 2019). Neuroblastoma (NB) is the most common solid, extracranial childhood tumor. "We also observed CLASP2 relocalization to MT plus-ends upon insulin or IGF-1 treatment in neuroblastoma cells or neurons, respectively." (PMID 30787869, 2019). "We have studied the functions of CLASP1 and -2 in differentiating N1E-115 neuroblastoma cells, and in Clasp2 mouse knockout (KO) neurons." (PMID 30787869, 2019). "To address CLASP1 and CLASP2 function and behavior in neuronal cells, we used the N1E-115 mouse neuroblastoma cell line." (PMID 30787869, 2019). "Here, we reveal distinct functions for the CLASPs in N1E-115 neuroblastoma cells with CLASP1 stimulating neurite outgrowth and CLASP2 acting as a break." (PMID 30787869, 2019). "Here, we show that in differentiating N1E-115 neuroblastoma cells CLASP1 and CLASP2 differ in their accumulation at MT plus-ends and display different sensitivity to GSK3-mediated phosphorylation, and hence regulation." (PMID 30787869, 2019). "Moreover, WB analyses also indicated that in neuroblastoma cells CLASP2 is phosphorylated by GSK3 but CLASP1 is not." (PMID 30787869, 2019).
Thrombocytopenia (1 paper, 2024). A reduction in the number of circulating thrombocytes. "CLASP2 is essential for haematopoietic stem cell development, and knockout of CLASP2 causes thrombocytopenia in mice." (PMID 38835242, 2024).
cancer (3 papers, 2017 to 2023). A tumor composed of atypical neoplastic, often pleomorphic cells that invade other tissues. "CLASP2 is closely associated with the function of microtubules which regulate invasive protrusions, termed podosomes and their cancer counterpart’s invadopodia." (PMID 28166762, 2017). "CLASP2 could play an essential role in cytoskeletal polarization during metastasis and invasion of cancer cells." (PMID 28166762, 2017).
infection (2 papers, 2021 to 2023). The state of being infected such as from the introduction of a foreign agent such as serum, vaccine, antigenic substance or organism. "Cytoplasmic linker-associated protein 2 (CLASP2) is a TIP that capsid utilizes to stabilize microtubules and promote early infection." (PMID 33572761, 2021). "CLASP2 has been discovered as a host component that allows HIV to induce microtubule stability and boost early infection in natural target cell types." (PMID 38022651, 2023).
tumor (2 papers, 2017 to 2023). "In our study, univariable and multivariable analysis suggested that high expressions of CLASP2 in tumor and urine cells were risk factors for progression within 2 years." (PMID 28166762, 2017). "Area under curve (AUC) of ROC of tumor grade was compared with those of CLASP2, E-cadherin and Vimentin mRNA levels in tumor and urine." (PMID 28166762, 2017). "Clasp2 expression, indeed, was found to be upregulated in bladder cancer tissues, where it seems to promote endothelial-to-mesenchymal transition (EMT) and to be associated with tumor progression, gaining attention as a prognostic factor." (PMID 38066968, 2023). "The levels of mRNA of CLASP2 and EMT-related markers in tumor and urine samples were tested by RT-PCR." (PMID 28166762, 2017). "Similarly, enrichment analysis on histological human specimens of lung cancer defined CLASP2 and its paralogue, CLASP1, as predictive markers of tumor recurrence." (PMID 38066968, 2023). "Significant differences were shown in the levels of CLASP2 and E-cadherin mRNA in the both tumor and urine between the patients with and without 2-years progression (P <0.01)." (PMID 28166762, 2017). "Moreover, we investigated the mRNA levels of CLASP2 and EMT-related markers in both TURBT tumor samples and the corresponding patients’ urine." (PMID 28166762, 2017). "The combination (CLASP2 + E-cadherin mRNA in urine) could better discriminate the patients with or without 2-years progression compared with tumor grade after TURBT." (PMID 28166762, 2017). "However, the results showed that mRNA levels of individual CLASP2 or other two EMT-related markers in tumor and urine could not discriminate better than grade." (PMID 28166762, 2017). "None of mRNA levels of individual CLASP2 or the EMT-related markers in tumor and urine showed better discriminating value than tumor grade." (PMID 28166762, 2017).
CLASP2 also shares sentences with these, for which no sentence is quoted: asthma (1 paper); autism spectrum disorder (1); epilepsy (1); inflammation (1); male infertility (1); prostate tumor (1); Testis (1).